RPS24 (ribosomal protein S24)
Description:
Component of the small ribosomal subunit. The ribosome is a large ribonucleoprotein complex responsible for the synthesis of proteins in the cell. Required for processing of pre-rRNA and maturation of 40S ribosomal subunits. Part of the small subunit (SSU) processome, first precursor of the small eukaryotic ribosomal subunit. During the assembly of the SSU processome in the nucleolus, many ribosome biogenesis factors, an RNA chaperone and ribosomal proteins associate with the nascent pre-rRNA and work in concert to generate RNA folding, modifications, rearrangements and cleavage as well as targeted degradation of pre-ribosomal RNA by the RNA exosome.
Synonyms: S24; eS24; DBA3
Tractability: Small molecule: an approved drug acts on it; a structure with a bound ligand is known; a high-quality ligand is known. PROTAC: UniProt records ubiquitination sites on it; ubiquitination databases record sites on it; its protein half-life has been measured; a small molecule that binds it is known. Other modalities: a drug acting on it is in phase 2 or 3 trials.
Target class: Other cytosolic protein
Gene: Protein-coding gene on chromosome 10 (78,033,746 to 78,056,813, forward strand). Ensembl gene ENSG00000138326.
Subcellular location: Cytoplasm; Nucleus, nucleolus
Subcellular location (Human Protein Atlas): Cytosol; Endoplasmic reticulum
Pathways (Reactome):
Metabolism of proteins: Eukaryotic Translation Termination; Formation of a pool of free 40S subunits; Formation of the ternary complex, and subsequently, the 43S complex; GTP hydrolysis and joining of the 60S ribosomal subunit; L13a-mediated translational silencing of Ceruloplasmin expression; PELO:HBS1L and ABCE1 dissociate a ribosome on a non-stop mRNA; Peptide chain elongation; Ribosomal scanning and start codon recognition; SRP-dependent cotranslational protein targeting to membrane; Translation initiation complex formation; ZNF598 and the Ribosome-associated Quality Trigger (RQT) complex dissociate a ribosome stalled on a no-go mRNA
Disease: SARS-CoV-1 modulates host translation machinery; SARS-CoV-2 modulates host translation machinery; Viral mRNA Translation
Metabolism of RNA: Major pathway of rRNA processing in the nucleolus and cytosol; Nonsense Mediated Decay (NMD) enhanced by the Exon Junction Complex (EJC); Nonsense Mediated Decay (NMD) independent of the Exon Junction Complex (EJC)
Cellular responses to stimuli: Response of EIF2AK4 (GCN2) to amino acid deficiency
Developmental Biology: Regulation of expression of SLITs and ROBOs
Metabolism: Selenocysteine synthesis
Gene Ontology:
Molecular function: RNA binding; structural constituent of ribosome; translation initiation factor binding
Biological process: cytoplasmic translation; erythrocyte homeostasis; ribosomal small subunit biogenesis; rRNA processing; translation
Cellular component: cytoplasm; cytosol; cytosolic ribosome; cytosolic small ribosomal subunit; endoplasmic reticulum; membrane; nucleus; small ribosomal subunit; small-subunit processome; nucleoplasm; nucleolus; ribosome
Genetic constraint (gnomAD): Loss-of-function variants: 0 observed, 16.44 expected, observed/expected ratio (o/e) 0, 90% interval 0 to 0.18. The upper end of that interval is the gene's LOEUF score, 0.18, which puts it in group 1 of 6, group 1 being the genes least tolerant of losing a copy. Missense variants: 100 observed, 157.62 expected, observed/expected ratio (o/e) 0.63, 90% interval 0.54 to 0.75. Synonymous variants: 72 observed, 55.59 expected, observed/expected ratio (o/e) 1.3, 90% interval 1.07 to 1.58.
Gene-disease validity (ClinGen):
ClinGen rates the evidence that RPS24 causes each of these diseases.
Diamond-Blackfan anemia (autosomal dominant): Definitive. A congenital aregenerative and often macrocytic anemia with erythroblastopenia.
Homologues: Orthologues: chimpanzee RPS24 (100% identical), dog RPS24 (100% identical), macaque RPS24 (100% identical), tropical clawed frog rps24 (100% identical), zebrafish rps24 (92% identical), Drosophila melanogaster RpS24 (77% identical), Caenorhabditis elegans T07A9.14 (25% identical).
Diseases named in the same sentence as RPS24 in open-access papers:
RPS24 is named in the same sentence as 54 diseases in open-access papers, as found by Europe PMC text mining. Sharing a sentence is not in itself a finding about the gene and the disease. The quoted sentences say what the papers report.
Diamond-Blackfan anemia (23 papers, 2009 to 2025). "Mutations in specific RPs, such as RPL5, RPL11, RPS17, RPS19, and RPS24, have been associated with Diamond Blackfan Anemia (DBA)." (PMID 39086661, 2024). "Further, mutations in several ribosomal protein (RP) genes, such as RPS19, RPL5, RPL11, RPL35A, RPS10, RPS17, and RPS24, cause Diamond-Blackfan anemia (DBA)." (PMID 38820160, 2024). "Mutations in RpS24 are associated with Diamond-Blackfan Anaemia and in Drosophila have been shown to cause developmental delays which were rescued by expressing synaptic vesicle proteins in serotonergic neurons." (PMID 37047316, 2023). "Mutations in RPS24, which lower the levels of this small ribosomal subunit protein, cause Diamond-Blackfan Anemia (DBA)." (PMID 31109297, 2019). "As mutations in the small ribosomal subunit protein RPS24 cause Diamond-Blackfan Anemia (DBA), we explored this uORF further." (PMID 31109297, 2019). "RPS17 along with RPS19 and RPS24 have been linked to diseases in humans including Diamond-Blackfan Anemia, an erythroid aplasia resulting in a deficiency of red blood cell precursors in the bone marrow." (PMID 25853866, 2015). "Interestingly, mutations in RPS24 cause Diamond Blackfan anemia; with a high prevalence of congenital heart disease (~ 30%)." (PMID 40382596, 2025). "For example, mutations in RpS19, RpS17, RpS24, RpL35a, RpS7, RpL5, RpL11, RpS10 and RpS26 have been associated with the human disease Diamond Blackfan Anemia (DBA), a dominant autosomal bone marrow failure syndrome, characterised by hypoplastic anemia with a predisposition to leukemia." (PMID 22194697, 2011). "Interestingly, mutations in human ribosomal proteins (including RPS24) cause Diamond-Blackfan anemia (DBA, RPS24 is DBA3 MIM:610629); a dominant Minute-like condition characterized by growth impairment, bone marrow failure, and congenital malformations with a high penetrance of CHD (~ 30%)." (PMID 34906219, 2021). "For example, the knockdown of RPS19 or RPS24 in primary fibroblast cells from Diamond-Blackfan anemia (DBA) patients triggered cell cycle arrested at the G1 phase and G2/M phase, respectively, leading to a marked reduction in cell proliferation capacity." (PMID 29045730, 2017). "Mutations of RPS19, as well as of two other ribosomal proteins, RPS24 and RPS17, have been linked to the rare congenital disease Diamond-Blackfan Anemia." (PMID 28680364, 2016). "In humans, mutations in RPs have been implicated in hematopoetic disorders, most notably Diamond-Blackfan anemia (DBA), which has been attributed to mutations in RPS19, RPS26, RPS24, RPS17, RPS10, RPS7, RPL35a, RPL26, RPL11, and RPL5." (PMID 23382688, 2013). "Diamond-Blackfan anemia is associated with an increased frequency of OS and mutations in ribosomal genes (i.e., RPS19, RPS24 and RPS17)." (PMID 21619704, 2011). "Four RP genes, RPS19 RPS24, RPS17, and RPL35a are known to be mutated in Diamond-Blackfan anemia (DBA; MIM 105650), a congenital erthyroid aplasia characterized by macrocytic anemia." (PMID 19129914, 2009). "There are abundant genetic and experimental evidences demonstrate that Diamond-Blackfan anemia (DBA), a dominant autosomal bone marrow failure syndrome, is due to mutations in ribosomal genes including RPS19, RPS24, RPL5, RPL11, and RPS29, etc8-12." (PMID 31523176, 2019). "The most well characterized is Diamond Blackfan anemia (DBA), which results from haploinsufficiencies in several different RP genes (RPS24/eS24, RPS17/eS17, RPL35A/eL33, RPL5/uL18, RPL11/uL5, RPS7/eS7, RPL36/eL36, RPS15/uS19, RPS27A/eS31) and RPS19/eS19, which is mutated in 25% of patients." (PMID 33565275, 2021).
prostate carcinoma (8 papers, 2017 to 2025). A carcinoma that arises from epithelial cells of the prostate gland. "For example, RPS19, RPS21, and RPS24 can be used as biomarkers for prostate cancer, and ribosome dysfunction is associated with the pathogenesis of nasopharyngeal carcinoma and can promote breast cancer metastasis." (PMID 34796111, 2021). "In GO enrichment analysis for up regulated genes, genes such as EIF4E and RPS24 were associated with cancer cell proliferation in many cancer types such as prostate cancer and colorectal cancer cells, but these genes may be responsible for the proliferation of GBM cells." (PMID 31137733, 2019). "Surprisingly, studies found that RPS24 was highly expressed in prostate cancer and colorectal cancer and drove tumor progression." (PMID 36614249, 2023). "Amongst the genes containing ESRP2-repressed exons that were also skipped in response to androgen stimulation were DOCK7 (exon 23), which encodes a guanine nucleotide exchange factor involved in cell migration; and RPS24 (exon 5), a gene that is highly expressed in prostate cancer." (PMID 31478829, 2019). "Our results show that RPS19, RPS21 or RPS24 are upregulated in malignant tissue and may serve as putative biomarkers for prostate cancer." (PMID 29016636, 2017). "In the same study, hypoxia led to an increase in the alternative splicing of eS24/RPS24 in U87MG (glioblastoma) and PC3 (prostate cancer) monolayers and spheroids relative to normoxia, which resulted in the removal of three amino acids at the C-terminus, including a lysine." (PMID 37047306, 2023).
colorectal cancer (6 papers, 2019 to 2023). A primary or metastatic malignant neoplasm that affects the colon or rectum. "RPS24 significantly promoted colorectal cancer (CRC) cells’ proliferation rate and increased CRC risk in patients." (PMID 34760386, 2021). "RPS24 is a gene that significantly promotes CRC cell proliferation, and knockdown of RPS24 can inhibit colorectal cancer cell migration and proliferation in vitro." (PMID 36505481, 2022). "The RPS24 that we found to be upregulated in AA-treated colon tissue and significantly highly expressed in COAD tissue based on TCGA analysis has been previously reported to promote colorectal cancer cell migration and proliferation in vitro." (PMID 37888706, 2023).
colon carcinoma (5 papers, 2017 to 2024). "RPS24 was linked with the proliferation of colon cancer cells, but this gene may be linked with the proliferation of GBM cells." (PMID 31137733, 2019). "Knockdown of other RPs such as RPL9 and RPS24 suppressed colon carcinoma cell growth in vitro and human CRC xenografts in nude mice." (PMID 31506518, 2019). "The efficacy of RPS24 as a target for diagnosis or treatment of colon carcinoma has previously been evaluated following the discovery that rps24 knockdown in CRC cell lines (HCT116 and HT-29) reduced cell proliferation and hindered cell migration rate." (PMID 29016636, 2017). "Notably, RPS24 plays a pivotal role in human colon cancer, with its knockdown leading to significant inhibition of colon cancer cell proliferation, suggesting its potential application in colon cancer diagnosis." (PMID 39684863, 2024). "Moreover, a recent study reported that the inhibition of RPS24 expression with small hairpin shRNA can suppress cell proliferation and migration in colon cancer." (PMID 36614249, 2023). "It was also found that RPS24 could promote cell proliferation and migration in human colon cancer." (PMID 36614249, 2023). "The study went on to conclude that the rps24 gene may have a critical role in colon cancer." (PMID 29016636, 2017).
breast carcinoma (4 papers, 2018 to 2025). "Here, we aimed to examine RPS24 AS patterns across breast cancer cell lines and associated isoforms, components and regulatory mechanisms in estrogen receptor (ER)-positive (ER+) breast cancer." (PMID 41258078, 2025). "When ER-alpha binding sites were repressed using CRISPR interference, RPS24 emerged as one of the top 15 genes of which the loss significantly compromised breast cancer cell fitness (right)." (PMID 41258078, 2025). "To further investigate the relationship between ESR1 and RPS24 AS, we analyzed transcriptome data from two luminal A-type breast cancer cell lines (MCF7 and T47D) harboring mutations in the ligand-binding domain of the ESR1 gene, a common occurrence in metastatic breast cancer." (PMID 41258078, 2025). "We next investigated the clinical relevance of RPS24 ex4:3 bp isoform expression patterns in cohorts of patients with breast cancer." (PMID 41258078, 2025). "Our comprehensive investigation into RPS24 AS in breast cancer reveals a complex regulatory network centered on the ex4:3 bp microexon isoform." (PMID 41258078, 2025). "The three RPS24 isoforms present in breast cancer exhibited variations in their C-terminal amino acid composition." (PMID 41258078, 2025). "We investigated the regulation of the RPS24 ex4:3 bp isoform in response to two key elements of breast cancer treatment: pathway inhibition and drug resistance." (PMID 41258078, 2025). "In summary, our findings reveal RPS24 AS as a sophisticated regulatory mechanism integrating multiple signaling pathways critical to breast cancer biology." (PMID 41258078, 2025). "We investigated the differences in RPS24 AS isoform expression across molecular subtypes in the CCLE breast cancer dataset." (PMID 41258078, 2025). "The objective was to investigate the clinical significance of RPS24 AS patterns by exploring its potential as a predictive biomarker for drug resistance and epithelial differentiation status in ER+ breast cancer." (PMID 41258078, 2025). "To assess the diversity among breast cancer cell lines, we first investigated the distribution of RPS24 AS isoforms in 51 breast cancer cell lines from CCLE24 and observed profound heterogeneity in isoform composition between cell lines." (PMID 41258078, 2025). "This sophisticated interplay reveals a key regulatory mechanism where RPS24 AS actively participates in maintaining ER+ breast cancer cell identity and survival, extending beyond merely being a downstream target of ER signaling." (PMID 41258078, 2025). "Here we identified notable variations in ribosomal protein S24 (RPS24) splicing patterns across breast cancer subtypes and investigated this novel regulatory mechanism." (PMID 41258078, 2025). "Our study highlighted a significant correlation between the expression levels of a specific RPS24 AS isoform and the epithelial-mesenchymal transition process in lung and breast cancers." (PMID 38853173, 2024). "As the roles of ribosomal proteins in breast cancer progression and treatment response continue to emerge, understanding RPS24 AS behavior in breast cancer could provide valuable insights into disease mechanisms." (PMID 41258078, 2025). "Having established the regulatory relationship between ER-alpha and RPS24 AS, we next aimed to understand how this splicing event responds to therapeutic interventions and contributes to treatment resistance, which are critical aspects of breast cancer management." (PMID 41258078, 2025).
congenital heart disease (4 papers, 2018 to 2025). A heart disease that is present at birth. "Loss-of-function mutations in RPS24 have been associated with congenital heart disease, even though they display incomplete penetrance." (PMID 38002903, 2023). "This is also supported by the recent report of two unrelated patients with congenital heart disease and mutations in RPS24 who were not anemic." (PMID 29766597, 2018).
hepatocellular carcinoma (3 papers, 2018 to 2024). A malignant tumor that arises from hepatocytes. "lncRNA associated with microvascular invasion in hepatocellular carcinoma (MVIH) is encoded in the intron of ribosomal protein S24 (RPS24) gene." (PMID 30477236, 2018). "To investigate the clinical effects of RPS24 on patients with hepatocellular carcinoma, we classified the HCC patients into a “high group” (n = 45) and “low group” (n = 41) based on the IHC staining indicators of RPS24 expression." (PMID 36614249, 2023).
osteosarcoma (3 papers, 2022 to 2025). A usually aggressive malignant bone-forming mesenchymal neoplasm, predominantly affecting adolescents and young adults. "In response to stress, uS3/RPS3, uS4/RPS9, uS17/RPS11, eS24/RPS24, eL6/RPL6, uL13/RPL13A, eL14/RPL14, eL30/RPL30, eL42L/RPL36AL, and RACK1 in U2OS (human osteosarcoma) cells have O-linked β-N-acetylglucosamine (O-GlcNAc) modifications." (PMID 37047306, 2023).
COVID-19 (2 papers, 2022 to 2023). A disease caused by infection with severe acute respiratory syndrome coronavirus 2. "In addition, we deployed validation experiments for local splicing changes of 6 genes (CD74, LRRFIP1, SH3GLB1, MACF1, RPS24 and PDLIM5) between 9 COVID-19 cases and 10 controls by semiquantitative reverse transcription (RT)-PCR." (PMID 35421082, 2022).
prostate tumour (2 papers, 2019 to 2023). "(G) Percentage splicing inclusion (PSI), quantified by RT-PCR, of RPS24 exon 2 within nine matched samples of prostate tumour and adjacent normal tissue (statistical significance calculated using t test)." (PMID 31478829, 2019). "Further qRT-PCR analysis of an independent cohort confirmed more frequent skipping of DOCK7 (exon 23) and RPS24 (exon 5) in prostate tumour tissue compared to normal prostate." (PMID 31478829, 2019). "Notably, in line with the event identified in our study, exon 5 of RPS24, an ESRP2-repressed exon, is frequently skipped in prostate tumour tissue and correlates with hypoxia in PCa samples, suggesting its AS may serve as a tumour hypoxia marker." (PMID 37924098, 2023).
cardiomyopathy (1 paper, 2025). A disease of the heart muscle or myocardium proper. "We observed dysregulated alternative splicing of PFDN5 and RPS24 is associated with the development of cardiomyopathy.Splicing defects in PFDN5 impair cytoskeletal protein folding, while RPS24 dysregulation affects their translation, disrupting actin and tubulin homeostasis." (PMID 40382596, 2025). "We identified alternative transcripts of RPS24 and PFDN5 genes among childhood cancer survivors with anthracycline-induced cardiomyopathy." (PMID 40382596, 2025). "RPS24 transcript ENST00000372360 and PFDN5 transcript ENST00000551018 had higher expression in patients with cardiomyopathy with direct correlation of intron retention and exon skipping to lower transcript level expression in controls." (PMID 40382596, 2025). "Splicing alterations resulting in differential expression of splicing isoforms in RPS24 and PFDN5 could compromise protein homeostasis, cardiac structure, and stress response, ultimately contributing to cardiomyopathy (Central Illustration)." (PMID 40382596, 2025).
cholangiocarcinoma (1 paper, 2023). A carcinoma that arises from the intrahepatic biliary tree (intrahepatic cholangiocarcinoma) or from the junction, or adjacent to the junction, of the right and left hepatic ducts (hilar cholangiocarcinoma). "Furthermore, 28 types of tumors were examined for the mRNA level of RPS24, showing that RPS24 was elevated in most of the tumors, such as cholangiocarcinoma (CHOL), thyroid carcinoma (THCA), rectum adenocarcinoma (READ), and thymoma (THYM)." (PMID 36614249, 2023).
deficiencies (1 paper, 2016). "Similarly, RP genes with myeloid-lineage specificity in our analysis, such as RPS27L, RPS15, and RPS24, have been previously implicated in bone marrow deficiencies." (PMID 27884178, 2016).
heart failure (1 paper, 2025). Inability of the heart to pump blood at an adequate rate to meet tissue metabolic requirements. "In a previous study, characterization of mCpG in heart failure showed that RPS24 is associated with heart failure." (PMID 40382596, 2025). "Additionally, whole exome sequencing data showed that RPS24 mutations were associated with heart failure." (PMID 40382596, 2025).